SYP (synaptophysin)
Diseases named in the same sentence as SYP in open-access papers (continued):
Sharing a sentence is not in itself a finding about the gene and the disease.
small cell carcinoma (continued). "The small cell neuroendocrine carcinoma component was diffusely positive for synaptophysin and CD56, while they were negative for chromogranin." (PMID 40093349, 2024). "These phenotypically similar, small cell neuroendocrine cancers (SCNCs) are classified as high-grade, poorly differentiated small cell carcinomas that commonly express neuroendocrine markers like chromogranin A (CHGA), neural cell adhesion molecule 1 (NCAM1), and synaptophysin (SYP)." (PMID 39589879, 2024). "The immunohistochemical profile of a CK7−/CK20+ CUPs should include endocrine markers (Chromogranin, Synaptophysin and CD56) as this profile is unique to Merkel cell carcinomas and small cell carcinomas of the salivary glands, both with perinuclear “dot-like” CK20 staining." (PMID 29621151, 2018). "Synaptophysin and chromogranin are positive in small cell neuroendocrine carcinoma, but are consistently negative in BSCC." (PMID 29221167, 2017). "In the case of small cell carcinoma, immunohistological detection of CgA was negative, synaptophysin was focally positive and proliferative activity of tumour cells (Ki-67 index) was higher than 80%." (PMID 24695372, 2014). "As reported, positivity for synaptophysin can also be detected in pure RMS, and hence has little utility to differentiate rhabdomyosarcomatous tumors from other mimics with neuroendocrine differentiation such as small cell carcinoma." (PMID 21762516, 2011). "Tumors are negative for synaptophysin and chromogranin, which can be useful for distinguishing basaloid SCC from small cell carcinoma." (PMID 32892208, 2021). "Biopsy specimen stained positive for CK, CD56, NSE, BcL2, Synaptophysin, PAX-5, and TTF-1, but negative for Chromogranin, CD57, and NFP; consistent with small cell carcinoma." (PMID 30428872, 2018). "This demonstrated metastatic small-cell carcinoma positive for pan-cytokeratin (panCK) and thyroid transcription factor 1 (TTF1), but negative for other traditional markers of small-cell carcinoma such as 34BE12, CD56, synaptophysin, and chromogranin." (PMID 28487881, 2017). "Immunohistochemical investigation was positive for Synaptophysin and CD56, negative for Chromogranin A and Neuron Specific Enolase (NSE) and was consistent with the diagnosis of metastasis of NEC/small cell carcinoma with Ki-67 90% as additional poor prognostic factor." (PMID 32293342, 2020). "Careful interpretation of PAX5 without confirmation of a hematolymphoid origin (CD45, CD43) should be kept in mind since up to 30% of small cell carcinomas can be positive for PAX5, and some cases of small cell carcinoma may be negative or only patchy positive for keratins and synaptophysin." (PMID 37958219, 2023).
Stroke (39 papers, 2010 to 2026). Sudden impairment of blood flow to a part of the brain due to occlusion or rupture of an artery to the brain. "PDA-001 treatment in both young adult and older rat stroke models is associated with increased synaptophysin expression suggesting that enhanced synaptic plasticity may also contribute to the observed functional improvement." (PMID 24466174, 2014). "PHA treatment also reduced CD68+/SYP+ on both sides of the hippocampi (p<0.001) and GFAP+/SYP+ cells in the hippocampi ipsilateral to stroke injury (p<0.001)." (PMID 40661422, 2025). "We found more CD68+/SYP+ cells in the peri-atrophic region of old stroke mice than young stroke mice (p=0.045); in the ipsilateral side than the contralateral side of the hippocampi in the old stroke mice (p=0.035)." (PMID 40661422, 2025). "The old stroke mice also had more CD68+/SYP+ cells in the ipsilateral side of the hippocampi than in young stroke mice (p=0.042)." (PMID 40661422, 2025). "By modulating this pathway ketamine (in a mouse model of post-stroke depression) can restore dendritic spine density and the expression of synaptic proteins such as PSD-95 and SYP during stroke induced neurological damage." (PMID 41369360, 2025). "We demonstrated that rats treated with a combination of DBS and MNG increased synaptophysin, synapsin I, and p-synapsin I expressions in the peri-infarct tissue 35 days post-stroke compared with untreated rats." (PMID 39697542, 2024). "This is supported by previous studies indicating that BDNF enhances synaptophysin expression, thus contributing to synaptic plasticity and recovery post-stroke." (PMID 39519132, 2024). "Numerous research findings indicate that proteins such as BDNF, GAP43, PSD95, and synaptophysin play critical roles in neurogenesis, synaptic repair, and neural plasticity, all of which are crucial for functional recovery post-stroke." (PMID 39519132, 2024). "We then performed high-resolution confocal microscopy to analyze glial cell-mediated engulfment of the presynaptic protein SYP and the postsynaptic protein Homer-1 in the gliosis region at 14 days after stroke." (PMID 34836962, 2021). "To investigate the possibility that drNPC transplants influenced recovery by promoting synaptic plasticity, we examined the expression of synaptophysin, a presynaptic vesicle protein, in treated stroke-injured brains." (PMID 30747366, 2020). "Using immunohistochemistry and confocal imaging, we compared the mean pixel intensity (MPI) of synaptophysin expression in the perilesional tissue of stroke-injured mice that received drNPCs (n = 6) and those that received vehicle-only injections (n = 9)." (PMID 30747366, 2020). "In contrast, the expression of SYP was reduced markedly at 4 days after CD200R Ab injection post-stroke (group main effect, F4, 30 = 23.64, P < 0.0001)." (PMID 32473633, 2020). "It has previously been reported that enhanced synaptic plasticity measured through an increase in synaptophysin expression mediates treatment benefits after stroke." (PMID 32973489, 2020). "The expression of synaptophysin was increased in the rGDF11 treated group compared to vehicle-treated stroke mice (p<0.05)." (PMID 32365331, 2020). "Since previous studies showed that citicoline led to the upregulation of synaptophysin in the penumbra region in the setting of stroke recovery, we wanted to investigate the effect of this molecule in the retina, a tissue embriologically brain-derived." (PMID 30127248, 2018). "Further, PEG-IGF-I treatment increases GFAP expression when given early (3 hrs post-stroke), increases Synaptophysin expression and increases neurogenesis in young and aged." (PMID 28325900, 2017). "Though study suggested statin was capable of increasing neurogenesis, synaptic protein and synaptophysin after stroke, Simvastatin combined with BMSC in the present study did not obviously promote neurogenesis compared with BMSC treatment." (PMID 27465579, 2016).
Stroke (continued). "Stroke rats treated with hUTC demonstrated significant increase in Synaptophysin expression in the ischemic brain compared to co-control." (PMID 23342081, 2013). "The combination treatment of stroke significantly induces an additive increase in synaptic plasticity identified by increased Synaptophysin expression in the ischemic brain when compared to the monotherapy with BMSCs." (PMID 24284395, 2013). "Stroke induces an increase in mature BDNF expression which coincides with the increase of synaptophysin both in ipsilateral cortex and hippocampal territories." (PMID 24236179, 2013). "Exercise resulted in a significant increase in synaptophysin expression both in control (+112%) and stroke rats (+238%)." (PMID 22962604, 2012). "In addition, the expression of synaptic plasticity‐associated proteins Synaptophysin, PSD95 and GAP43 in the hippocampus was significantly decreased following stroke, which were upregulated by IL‐2:IL‐2 Ab complex and inhibited by 4‐CIN." (PMID 41552852, 2026). "A recent study using directly reprogrammed human neural precursor cell transplants in mice after deliberate stroke shows synaptogenesis upregulation and increased expression of synaptophysin in the ipsilesional hemisphere of the transplanted brain, thereby promoting functional recovery." (PMID 34209997, 2021). "In the same manner, activating microglia M2 factor expression could improve the neuron connection of stroke mice along with reductions in elevated proinflammatory molecules and standardization of synaptophysin and PSD-95 expression." (PMID 32908485, 2020). "Most interesting, brains that received drNPC transplants had higher levels of synaptophysin in the perilesional stroke-injured cortex, supporting the idea that synaptogenesis may underlie the drNPC-mediated recovery." (PMID 30747366, 2020). "In addition, there was significant increase in vascular and synaptophysin immunoreactivity in stroke areas of rats that received In-111 labeled hUTC." (PMID 23217090, 2012). "Stroke decreased synaptophysin expression in the IBZ of the striatum compared to the normal mice." (PMID 20140248, 2010). "Recognizing the critical roles of proteins such as GAP43, PSD95, and synaptophysin in synaptic plasticity and recovery following stroke, we aimed to assess whether rNPFF treatment could increase the expression of these markers, thereby supporting synaptic integrity under ischemic conditions." (PMID 39519132, 2024). "Early post-treatment with psilocybin improved locomotor behavior, upregulated the expression of MAP2 and synaptophysin, and down-regulated the expression of IBA1 in the stroke brain." (PMID 39379834, 2024). "Similarly, in a rat model of stroke, CIMT resulted in the downregulation of this signaling pathway in the region of the lesioned cortex and the upregulation of markers such as growth-associated protein-43, synaptophysin, vGlut1, and postsynaptic density-95 in the denervated cervical spinal cord." (PMID 39273353, 2024). "We observed a restoration of MBP and synaptophysin levels in the MCAo GDF11 group in the peri-infarct area and CC at 30 days after stroke." (PMID 32365331, 2020). "Protein levels of synaptophysin were significantly reduced in the infarct (p = 0.0040), thalamus (p = 0.0019), and hippocampus (p = 0.0042) of TTC− stroke." (PMID 31417355, 2019). "APX3330 significantly promotes myelin density (p<0.05, n=7/group) and synaptophysin expression (p<0.05, n=7/group) in the IBZ compared to PBS treated control T1DM stroke rats." (PMID 29896433, 2018). "An elevated expression of synaptophysin, was detected in PUR-treated animals when compared with VEH at 14 d after stroke." (PMID 25341035, 2014). "Combination BMSCs and Niaspan treatment of stroke in diabetic rats increases the expression of CNPase, NG2, LFB, BS, Synaptophysin and SMI31 in the ischemic brain." (PMID 24284395, 2013).
Stroke (continued). "In another context, psilocybin, administered post-stroke, improves motor recovery, reduces neuroinflammation, and promotes neuroplasticity by activating the TrkB receptor and increasing levels of BDNF, MAP2, and synaptophysin." (PMID 41369360, 2025). "In addition, stroke + MT mice had lower levels of synaptophysin and PSD-95 than stroke mice, indicating ameliorated synaptic plasticity impairment." (PMID 38786094, 2024). "Upregulation of SNAP25 was found to be a synaptic response to ischemic damage in the hippocampus of gerbils two days after stroke, while others have found a prominent decrease of SNAP25 and synaptophysin for the same time point in the stroked gerbils that were subsequently incremented at 14 days." (PMID 38769196, 2024). "In the Stroke + Mexidol group, the synaptophysin level in the penumbra was increased compared to that in the Stroke + Saline group but not that in the Stroke + Semax group (p < 0.01)." (PMID 33806692, 2021). "Our data also demonstrate that combination treatment of stroke in diabetic rats significantly increased Synaptophysin and SMI31 expression compared to non-treatment T1DM control." (PMID 24284395, 2013). "In our stroke model, we observed a pronounced short-term PGC-1α activation, evidenced by a significant upregulation of PGC-1α-dependent proteins: NRF1, TFAM, catalytic subunits of the substrate-binding sites of the respiratory chain (NDUFV2 and SDHA), VEGF, and SYP." (PMID 33806692, 2021). "Furthermore, the concentration of synaptophysin, which is a neuronal synaptic vesicle that participates in synaptic transmission, was higher in the temporal cortex of VaD group with respect to AD, as well as in stroke subjects who did not develop dementia." (PMID 32340195, 2020). "Increasing the expression of LFB, BS, Synaptophysin, and SMI31 in T1DM-MCAo rats by combination treatment may contribute to improvement of white matter remodeling and synaptic plasticity in the ischemic brain, which may enhance functional outcome after stroke in diabetic rats." (PMID 24284395, 2013).
carcinoid (38 papers, 2004 to 2025). "Synaptophysin was positive in the carcinoid component, with few scattered cells staining in the strumal component." (PMID 40428242, 2025). "The final pathology of the tumor revealed a well-differentiated carcinoid tumor invading the muscularis mucosa with the tumor staining positive for synaptophysin, chromogranin, and CD56, with less than 2% Ki-67 positive." (PMID 39974256, 2025). "Biopsy results showed well-differentiated carcinoid tumor staining positive for synaptophysin, chromogranin, and CD56, with less than 3% Ki-67 positive." (PMID 39974256, 2025). "Although these cells mildly resembled luteinized ovarian stromal cells, they stained positive for synaptophysin, as did the carcinoid tumor." (PMID 40428242, 2025). "Histopathological examination confirmed a diagnosis of Grade 1 NET (typical carcinoid), supported by elevated levels of Synaptophysin and Chromogranin A on immunohistochemistry." (PMID 39268308, 2024). "For example, c-kit (CD117) or DOG1 is present in GISTs; desmin in leiomyomas; S-100 in schwannomas; smooth muscle actin in glomus tumors; anaplastic lymphoma kinase in inflammatory myofibroblastic tumors; and chromogranin A and synaptophysin in carcinoids." (PMID 38983989, 2024). "The final histopathological diagnosis was a typical carcinoid with positive chromogranin A, synaptophysin, and CD56, a Ki-67 labeling index of 5 %, and pathological stage IA3 with T1cN0M0, which was consistent with the intraoperative diagnosis." (PMID 39427400, 2024). "Carcinoids are consistently and diffusely positive for all standard NE markers (synaptophysin, chromogranin A, CD56) and INSM1." (PMID 34663914, 2022). "While virtually all carcinoids are positive for synaptophysin and chromogranin A, their expression is highly variable in NECs." (PMID 34663914, 2022). "As expected, immunohistochemical evaluation confirms the duality of the disease, with expression of specific markers both of thyroid (thyroglobulin, TTF1, calcitonin) and carcinoid (chromogranin A, synaptophysin, NSE and CD56)." (PMID 35528006, 2022). "Biopsy results from the initial admission characterized the obstructing infrahilar mass as a carcinoid tumor with positive synaptophysin/ chromogranin stain and low proliferation (Mib1 < 2%)." (PMID 36579277, 2022). "INSM1 tends to show high sensitivities overall but appears to underperform in comparison to CD56 and SYP in certain lung NETs such as carcinoid tumors and LCNECs." (PMID 34943408, 2021). "Carcinoid tumor can also be a diagnostic pitfall; however, a neuroendocrine appearance with rosette formation, “salt and pepper” chromatine, and positivity on CD56, Synaptophysin, and Chromogranin should lead to a proper diagnosis." (PMID 30691016, 2019). "Neuroendocrine differentiation of carcinoids is established by immunohistochemical identification of secreted and cytoplasmic products such as synaptophysin, neuron-specific enolase, and chromogranin." (PMID 30777035, 2019). "Immunohistochemical staining for synaptophysin or chromogranin in a conventional carcinoid will highlight sheets of cells, nearly every cell in the tumor, in contrast with the rare scattered peripheral endocrine cells seen in goblet cell carcinoid." (PMID 30244681, 2018). "Carcinoids were smaller in size and had higher synaptophysin and chromogranin A, but lower TTF-1 expressions." (PMID 25884169, 2015). "Carcinoid tumors, although they have similar morphology, are positive for cytokeratin, chromogranin, and synaptophysin." (PMID 26442165, 2015). "In the smaller carcinoids, expression of the neuroendocrine markers synaptophysin and chromogranin A was higher, but of TTF1 lower in comparison to LCNEC/SCLC." (PMID 25884169, 2015). "Immunohistochemical stains were consistent with the diagnosis of carcinoid tumor, with the majority of the cases presenting strong immunoreactivity for synaptophysin, chromogranin A, NCAM, and somatostatin receptor type 2." (PMID 25685590, 2015).